FABP7 (fatty acid binding protein 7)
Diseases named in the same sentence as FABP7 in open-access papers (continued):
Sharing a sentence is not in itself a finding about the gene and the disease.
tumor (continued). "Supporting these findings, the authors further showed that mutant FABP7 disrupts these effects, underscoring its role in tumor aggressiveness." (PMID 40243482, 2025). "FABP7 plays a key role in various cancers by regulating lipid metabolism, tumor stem cell properties, and the immune microenvironment." (PMID 40717587, 2025). "For these studies, we examined the differential expression of FABP7 and its modulated genes in tumor and adjacent normal tissues across all tumors in The Cancer Genome Atlas (TCGA)." (PMID 39596296, 2024). "This approach provides valuable insights but is inherently limited in establishing causal relationships or capturing the complex, dynamic interactions of FABP7 within the tumor microenvironment." (PMID 39596296, 2024). "Expanding this research to include a broader range of cell lines, as well as primary tumor samples, would improve the generalizability of these findings and provide a more nuanced understanding of FABP7’s role across various tumor contexts." (PMID 39596296, 2024). "Accumulating studies have shown a pro-tumoral role for FABP7, focusing on intracellular mechanisms within tumor cells and their influence on cell proliferation and migration." (PMID 39596296, 2024). "It would also be interesting to confirm that the association between high levels of FABP7 expression in GB tissues and a better prognosis is due to higher levels of DHA in the tumor microenvironment." (PMID 38803161, 2024). "Increased abundance of Fabp7 promotes cell migration in vitro, and Fabp7 is evident at the leading edges of infiltrative tumours." (PMID 36876733, 2023). "Silencing H2AZ2 also significantly decreased GSC tumor initiating cell frequency as revealed by the extreme limiting dilution assay, which tracked with reduced FABP7 (a GSC marker) levels." (PMID 35058574, 2022). "FABP7 and NDUFAB1 were proven to have relevance in immune cell infiltration and tumour mutation burden (TMB)." (PMID 35562758, 2022). "It is of particular note that FABP7 was specifically expressed in malignant cells from metastatic tumor tissues, suggesting its potential role in promoting NSCLC metastasis." (PMID 35269427, 2022). "Our work identifies a tumor cell-specific enhancement of pro-metastatic FABP7 and elucidates a previously unidentified mechanism for Wnt/β-catenin signaling deregulation in NSCLC." (PMID 35269427, 2022). "By analyzing transcriptomic changes specifically in metastatic NSCLC tumor cells at single-cell resolution in this study, we found that FABP7 was up-regulated prominently and promoted metastasis-related traits of NSCLC cells." (PMID 35269427, 2022). "In conclusion, FABP7 is up-regulated specifically in tumor cells of metastatic NSCLC and endows tumors with metastatic potency via impairing the ubiquitin-proteasomal degradation of β-catenin to activate canonical Wnt signaling." (PMID 35269427, 2022). "Considering these data suggesting a tight association between lipid raft function and tumor proliferation, FABP7 is strongly involved in tumor activation through controlling caveolae formation." (PMID 34716958, 2022). "Among all of these DEGs, FABP7 was the most remarkably up-regulated one with 19.7 times higher expression in metastatic tumor cells." (PMID 35269427, 2022). "It was found that mRNA level of FABP7 was considerably lower in residual tumor after NAC (GSE21997: p = 0.0264; GSE32646: p = 0.0075; GSE25055: p = 0.0004)." (PMID 33292226, 2020). "We observed an average overexpression of ~37 folds for MAOB and ~eight folds for FABP7 in grade III tumours compared to grade I, whilst RBP1 average grade III expression was analogous to that of grade I." (PMID 33167358, 2020). "Bulk transcriptomic analysis of eGFP+ tumor cells from these mice showed upregulation of specific stem cell markers, including Sox2, Gfap, Olig1, Olig2, Blbp (Fabp7) and Pdgfra31." (PMID 31863004, 2019).
tumor (continued). "FABP7 (fatty acid binding protein 7) transports the fatty acids toward the nucleus; in the same way, it supplies the LDs to promote tumor growth, and it appears increased by hypoxia." (PMID 29966227, 2018). "Studies on human tumors and tumor-derived cell lines have indicated both FABP7's potential involvement in tumorigenesis and usefulness as a tumor marker." (PMID 21771320, 2011). "Recently, it was reported that nuclear expression of FABP7 is restricted to infiltrative tumor types and related to EGFR amplification and over-expression as well as poor prognosis of GBM." (PMID 18826602, 2008). "In contrast, when neoplastic cells in another region of the same tumor had nuclear FABP7 immunoreactivity, the EGFR immunoreactivity was usually prominent." (PMID 16623952, 2006). "It has been previously reported that EGFR signaling induces FABP7 expression in a Ras-independent pathway in normal and tumor Schwann cells, providing evidence of possible interaction between these two proteins." (PMID 16623952, 2006). "We found that if a cluster of tumor cells had only cytoplasmic FABP7 immunoreactivity, the EGFR staining was minimal." (PMID 16623952, 2006). "Importantly, HIF-1α depletion eliminated FABP7 induction in tumor-conditioned macrophages, confirming its upstream regulatory role." (PMID 40765822, 2025). "Single-cell expression analysis revealed that KRT5 and FABP7 were highly enriched in tumor cells, UGT2B4 was predominantly expressed in epithelial cells, BIRC3 and KLRB1 were enriched in CD8+ T cells, while MRC1 and CD209 were highly expressed in monocytes/macrophages." (PMID 40612672, 2025). "Notably, this effect was liver-specific, as FABP7 KO increased splenic M2 macrophages in tumor-bearing mice." (PMID 40765822, 2025). "This discrepancy may arise from functional differences of FABP7 in different subcellular localizations or tumor microenvironments." (PMID 40717587, 2025). "Furthermore, macrophages within liver PMN and MMN tissues from tumor-bearing mice exhibited substantially higher FABP7 expression than those from tumor-free mice." (PMID 40765822, 2025). "Moreover, recent evidence suggests a more nuanced role for FABP7 in the tumor immune microenvironment." (PMID 40612672, 2025). "High serum levels of MDH1 and RNH1 and low tumor levels of FABP7 may enable STS to maintain low ROS levels, counteracting the effects of chemoradiotherapy." (PMID 38803161, 2024). "It has been suggested that an AA‐rich tumor microenvironment promotes FABP7‐expressing GB cell growth whereas a DHA‐rich microenvironment may inhibit tumor infiltration due to higher levels of DHA uptake and use." (PMID 38803161, 2024). "In addition to the primary tumor tissue analysis data, we examined the expression of FABP7 in multiple cell lines that exhibit phenotypic resemblance to various organs or tumor tissues." (PMID 39596296, 2024). "Literature-based annotations of the protein-coding genes (n = 26) downregulated in Fabp7-KO cells indicated that over half of these genes (n = 16, 61.54%) are oncogenic drivers that promote tumor progression by playing roles in proliferation, survival, metastasis, and drug resistance." (PMID 39596296, 2024). "While the underlying mechanisms warrant further investigation, it is tempting to speculate that the differential profiles of tumor immune infiltration modulated by FABP7 could contribute to the disparate outcomes observed between LGG and GBM patients." (PMID 39596296, 2024). "Addressing these limitations through further research may clarify the therapeutic potential of targeting FABP7 in a tumor-specific manner, especially given the growing interest in developing novel FABP7 inhibitors and advancing cancer immunotherapy." (PMID 39596296, 2024). "By analyzing single-cell RNA sequencing data, we found that fatty acid binding protein 7 (FABP7) was specifically up-regulated in tumor cells of metastatic NSCLC patients and might be a prognostic indicator for poor survival." (PMID 35269427, 2022).
tumor (continued). "Taken together, these data suggest that nuclear FABP7 is involved in cell proliferation of GB through caveolae function/formation regulated via epigenetic regulation of caveolin‐1, and this mechanism is critically important for IDH1wt tumor biology." (PMID 34716958, 2022). "Recent studies showed that FABP7 was significantly involved in the pathogenesis and progression of many types of cancer and could be used as a promising tumor marker." (PMID 36581948, 2022). "FABP7 is shown to have high affinity for n‐3 PUFAs, EPA (Kd 48 nm), and DHA (Kd 53 nm), monounsaturated n‐9 Oleic acid (Kd 47 nm), and these FAs have been reported to have a strong association with tumor biology." (PMID 34716958, 2022). "To examine whether FABP7 regulates tumor biology in in vivo system, we established the xenograft model using stable luciferase‐expressing U87 tumor." (PMID 34716958, 2022). "In addition, the single-cell-based analysis leads to the discovery of a tumor cell-specific and metastasis-specific expression pattern of FABP7." (PMID 35269427, 2022). "Furthermore, we examined the role of FABP7 in tumor proliferation using in vitro model and found that FABP7overexpression activated caveolae function and formation through the epigenetic regulation of caveolin‐1 via controlling nuclear acetyl‐CoA levels." (PMID 34716958, 2022). "Notably, among these FABPs, FABP7 displayed the most unique and specific expressional pattern in metastatic tumor cells, and showed the most prominent correlation between expression alteration and clinical prognosis." (PMID 35269427, 2022). "The tumor tissues displayed an enriched expression of transcription factors (e.g., Dlx2, Gbx2, Foxb1, and Nkx2.2) critical for brain development, tanycyte markers (e.g., Ptprz1, Fabp7, Crym, and Gja1), and differentiation markers (e.g., Dcx, Olig1, and Cspg5)." (PMID 33863883, 2021). "Emerging studies have indicated that FABP7 was significantly involved in pathogenesis and progression of multiple cancer types and could be useful as a tumor marker." (PMID 33292226, 2020). "Similarly, the fatty acid-binding protein FABP7 was also among the top concordantly expressed genes with its overexpression previously reported to enhance the proliferation and migration of many tumour types." (PMID 33167358, 2020). "Moreover, inhibition of lipid storage by FABP3 or FABP7 knockdown decreased tumor cell survival under hypoxia-reoxygenation and impaired tumorigenesis in vivo." (PMID 31835444, 2019). "Increased immunoreactivity of nuclear FABP7 correlated with poor prognosis of GBM, particularly in younger patients, and we sought to identify the molecular mechanism underlying this association by investigating EGFR expression in this tumor type." (PMID 16623952, 2006). "Furthermore, the pathways driven by these biomarkers, and the tumor FABP7 pathway, may constitute promising therapeutic targets for blocking ROS detoxification to overcome resistance to chemoradiotherapy in potential GB STS." (PMID 38803161, 2024). "However, despite the known role of FABP7 in tumor growth and progression, its impact on the TIME and prognosis in LGG and GBM remains largely unknown." (PMID 39596296, 2024). "High level of FABP7 may enhance tumor progression by inducing resistance to antiangiogenic drugs." (PMID 35783014, 2022). "Thus, while expression of FABP7 may promote GBM growth in an AA-rich tumor microenvironment, in a DHA-rich microenvironment, FABP7 may inhibit tumor infiltration as the result of increased DHA uptake and utilization." (PMID 34444824, 2021). "However, it remains unclear whether FABP7 positively or negatively regulates the immune checkpoint pathway in the tumour microenvironment, since PD-L1 was upregulated in cancer cells upon FABP7 knockdown." (PMID 31819188, 2020).
tumor (continued). "Our future studies will focus on analyses of additional RCC cell lines to determine whether the low frequency of FABP7 expression is a consequence of selecting tumor cells for in vitro growth, and if so, will provide new insights into regulation of FABP7 expression." (PMID 21771320, 2011). "Nuclear FABP7 may be induced by EGFR activation to promote migration of GBM tumor cells." (PMID 16623952, 2006). "Western blot analysis confirmed FABP7 upregulation in both the PMN and MMN stages of MC38 tumor-bearing mice." (PMID 40765822, 2025). "For example, the tumour cell subpopulation BC_P02T demonstrated a high level of KRT14, while the BC_P06T subpopulation was marked by pronounced expression of FABP7, highlighting heterogeneity." (PMID 39877290, 2025). "While HIF-1α levels remained unchanged in lung and bone PMN, liver macrophages from MC38 tumor-bearing mice exhibited significant upregulation of both HIF-1α and FABP7 compared to controls." (PMID 40765822, 2025). "To validate this observation, we employed flow cytometry to assess FABP7 expression in CLEC4F+ F4/80+ KCs and CX3CR1+ F4/80+ MoMFs from the liver PMN and MMN of MC38 tumor-bearing mice." (PMID 40765822, 2025). "In accordance with a role of LD formation in tumor development, FABP3 or FABP7‐knockout U87 cells subcutaneously xenografted show a delay in tumor growth initiation, decreased proliferation and decreased lipid staining." (PMID 38105543, 2025). "Small-molecule inhibitors targeting FABP7 (e.g., ART26.12) significantly inhibit tumor growth and prolong survival in animal models." (PMID 40717587, 2025). "The three tumor proteins of interest (AHSP, FABP7 and TJAP1) were downregulated in the STS group and were not identified in the proteome of serum samples from GB patients." (PMID 38803161, 2024). "It has been suggested that an AA-rich environment promotes FABP7-expressing GBM cell growth, while a DHA-rich environment inhibits tumor infiltration." (PMID 39596296, 2024). "For tumor samples, only three of the 5422 normalized proteins displayed significant downregulation in the STS group: FABP7, TJAP1 and AHSP." (PMID 38803161, 2024). "The TCGA‐GB transcriptomic dataset was used to validate the prognostic value of the three tumor proteins of interest (AHSP, FABP7 and TJAP1) at the mRNA level." (PMID 38803161, 2024). "Expression of radial glial cell signature genes (PAX6, SOX2, FABP7) and FGFR3 was confirmed in both the radial glial/astrocyte-like and tumor cell clusters, whereas PIK3R3 and AKT1 were only expressed in the tumor cell cluster." (PMID 38609519, 2024). "FABP7 has also been shown to be highly expressed in NSCLC patient tumor cells, and studies in NSCLC cell lines indicate that FABP7 exerts prometastatic effects via impaired β-catenin degradation leading to Wnt hyperactivation." (PMID 37207357, 2023). "Multivariate analysis showed that the high FABP7 expression, PRS type, tumor grade, age, chemotherapy status, and MGMT methylation status were independently predictive of OS in these patients." (PMID 35783014, 2022). "Using tumour immune cell infiltration-related analysis, the results illustrated that FABP7 and NDUFAB1 were significantly correlated with tumour immune cell infiltration." (PMID 35562758, 2022). "We found that the expressions of CCL1, FABP7, S100B, CTSW, and SEZ6 significantly decreased in the tumor tissue, the expression of CPLX2 and SPIB increased obviously in BC." (PMID 36581948, 2022). "Many of these proteins (FABP7, FASN and ELOVL2) are up-regulated in GBM patient-derived tumor stem cell cultures compared to more-differentiated adherent cells cultured in serum-containing medium." (PMID 34444824, 2021). "Taken together these data support the contention that translocation of FABP7 between nuclei and cytoplasm may play a role in tumor progression and further investigation should be undertaken to understand roles of FABP7 signaling and intracellular traffic in tumor biology." (PMID 25389781, 2014).
tumor (continued). "Overexpression of FABP7 in tumor tissue and urine of patients with RCC, led us to consider FABP7 as such a biomarker and to elucidate the regulation of its expression." (PMID 21771320, 2011). "After entering tumor cells, the siRNAs could inhibit HIF-1α expression and block the downstream fatty acid transporters fatty acid binding protein (FABP) 3 and FABP7 to deplete the lipid droplet pool in tumor cells." (PMID 41041050, 2025). "Moreover, tumor cells can induce FABP7 expression in CD8+ T cells, leading to T cell apoptosis and facilitating tumor immune escape." (PMID 40919170, 2025). "For example, FABP7 in GBM epigenetically reprograms to suppress immune-related gene expression while upregulating ferroptosis-resistance gene BMAL1, helping tumor cells evade immune clearance and ferroptosis, which demonstrates deep integration of metabolic regulation and epigenetics." (PMID 40717587, 2025). "To investigate whether hypoxia induces FABP7 expression and drives LD accumulation in liver PMN macrophages, we performed histological analyses of MC38 tumor-bearing mice." (PMID 40765822, 2025). "Furthermore, FABP7-induced lipid-laden macrophages were observed to deliver lipids to CD8+ T and tumor cells via exosomes." (PMID 40765822, 2025). "Consistent with the results from non-tumor samples, all the TIMGs that we identified (ENO1, MUC1, COL5A1, COL11A1, IL11, AIM2, JUNB) as well as FABP7, exhibited significantly or moderately elevated expression in multiple TCGA tumors, including GBM, compared to normal tissues." (PMID 39596296, 2024). "This aligns with recent studies showing that nuclear FABP7 levels are higher in wild-type IDH1 malignant GBM tumors compared to IDH1-mutant LGG tumors, differentially regulating cell proliferation and migration in these distinct tumor types." (PMID 39596296, 2024). "Taken together, these data suggest that nuclear FABP7 is involved in cell proliferation of GBM through caveolae function/formation regulated via epigenetic regulation of caveolin‐1, and this mechanism is critically important for the IDH1wt tumor biology." (PMID 34716958, 2022). "Although the ligands of FABP7 for tumor proliferation have not been specified, further investigation will determine this." (PMID 34716958, 2022). "Furthermore, the acetylation level of H3K27 on caveolin‐1 promoter was increased by FABP7wt overexpression, suggesting FABP7 regulates caveolae formation through the interaction with ACLY, leading to activated tumor proliferation." (PMID 34716958, 2022). "In combination, these data suggest that FABP7 may be able to hijack the brain’s normal developmental processes for the maintenance of GBM stemness and tumor infiltration in brain parenchyma." (PMID 34444824, 2021). "Our further research suggested that WAKMAR2 is crucial in regulating the tumour microenvironment and may function by regulating immune-related genes, including IL27RA, RAC2, FABP7, IGLV1-51, IGHA1, and IGHD." (PMID 34321580, 2021). "Further analysis of the genes FABP7 and STRAP in GSCs compared to tumor tissue may be especially efficacious." (PMID 32634135, 2020). "In clear contrast, the genes involved in FA desaturation (stearoyl-CoA desaturase, SCD5) and PUFA trafficking (fatty acid-binding protein 7, FABP7; acyl-CoA synthetase 4, ACSL4; phospholipase A2G2D, PLA2G2D) were upregulated in tumours with PI(18:0/20:3) accumulation." (PMID 31819188, 2020). "Therefore, it would be interesting to elucidate how the coordination of FABP7, ACSL4 and PLA2G2D in tumour microenvironment modulates the remodelling of membrane lipids as well as tumour immunity." (PMID 31819188, 2020). "The expression of FABP7 was frequently observed in the peripheral lesion of the tumor with viable cancer cell, while was not in the central lesion with necrotic tissue." (PMID 30442117, 2018).